URAD (ureidoimidazoline (2-oxo-4-hydroxy-4-carboxy-5-) decarboxylase)
Description:
Catalyzes the stereoselective decarboxylation of 2-oxo-4-hydroxy-4-carboxy-5-ureidoimidazoline (OHCU) to (S)-allantoin, a step in the uric acid degradation pathway following urate oxidation (By similarity). In humans, the protein appears to be poorly or not expressed, suggesting that this activity is likely not operative (Probable).
Synonyms: PRHOXNB
Tractability: No criterion of Open Targets' tractability assessment is met for any kind of drug.
Gene: Protein-coding gene on chromosome 13 (27,977,717 to 27,988,693, reverse strand). Ensembl gene ENSG00000183463.
Subcellular location: Peroxisome
Gene Ontology:
Molecular function: 2-oxo-4-hydroxy-4-carboxy-5-ureidoimidazoline decarboxylase activity; carboxy-lyase activity
Biological process: allantoin metabolic process; urate catabolic process
Cellular component: peroxisome
Genetic constraint (gnomAD): Loss-of-function variants: 3 observed, 2.23 expected, observed/expected ratio (o/e) 1.35, 90% interval 0.53 to 1.92. That is too few expected variants to judge how well the gene tolerates losing a copy. Missense variants: 163 observed, 121.76 expected, observed/expected ratio (o/e) 1.34, 90% interval 1.18 to 1.52. Synonymous variants: 70 observed, 49.56 expected, observed/expected ratio (o/e) 1.41, 90% interval 1.16 to 1.72.
Homologues: Orthologues: chimpanzee URAD (94% identical), macaque URAD (94% identical), rabbit URAD (84% identical), mouse Urah (14% identical), rat Urah (14% identical), Drosophila melanogaster CG30016 (12% identical), Caenorhabditis elegans R09H10.3 (12% identical), zebrafish urahb (12% identical), Caenorhabditis elegans ZK697.8 (11% identical), zebrafish uraha (10% identical). Paralogues in human: TTR (13% identical).
Diseases named in the same sentence as URAD in open-access papers:
URAD is named in the same sentence as 4 diseases in open-access papers, as found by Europe PMC text mining. Sharing a sentence is not in itself a finding about the gene and the disease. The quoted sentences say what the papers report.
hyperuricemia (1 paper, 2020). An abnormally high level of uric acid. "By comparing the important genes involved in urate production, including XOR, UOX, URAH, and URAD, we concluded that chickens are a preferred animal for the hyperuricemia model." (PMID 32245084, 2020).
URAD also shares sentences with these, for which no sentence is quoted: cholestasis (1 paper); cryptococcosis (1); infection (1).